CD4 (CD4 molecule)
Diseases named in the same sentence as CD4 in open-access papers (continued):
Sharing a sentence is not in itself a finding about the gene and the disease.
tumor (continued). "Tumor-infiltrating CD4+ T cells orchestrate the adaptive immune response through remarkable plasticity, and the expression patterns of exhaustion-related inhibitory receptors in these cells differ significantly from those of CD8+ T cells." (PMID 38868329, 2024). "We identified CD8+ T cells, resting memory CD4+ T cells, activated NK cells and activated DCs as essential prognostic indicators, which were combined to develop a Tumor‐infiltrating Immune Cell Score (TICS)." (PMID 38017652, 2024). "Recent studies have elucidated the role of lactate in modulating the functions of CD4+ T cells within the tumor microenvironment and in the context of chronic inflammation." (PMID 39766353, 2024). "Relative to responsive patients, non-responsive patients revealed a low specificity to normal or tumor tissues in the distribution of differentially expressed genes (DEGs) within the CD4+ T cell population." (PMID 38948071, 2024). "This same chemokine axis facilitates the entry of naive CD8 and CD4 into the tumor-draining lymph node, while CCR5–CCL5 facilitates their interactions with DCs." (PMID 38360737, 2024). "During cancer progression, antigens released by dying tumor cells are presented by antigen-presenting cells (APCs) to CD4+ or CD8+ T cells, resulting in immune activation and a cascade of events that are the foundation of cancer immunity." (PMID 38427670, 2024). "Meanwhile, CD4 + T cells downregulate interferon-γ and IL-2, increase the production of IL-4 and IL-5, further promoting tumor development." (PMID 39020276, 2024). "To identify which genes are involved in the T cell-dependent anti-tumor effect in tumors, we performed gene ontology (GO) enrichment analysis of CD4 and CD8 T cells between each treatment." (PMID 39534532, 2024). "When mismatch repair-deficient (MMRd) and MMR-proficient (MMRp) CRC samples were compared, IFNβ expression in cluster 3 and cluster 4 CD4+ T cells (positive for CXCL13) was found to be significantly greater in the MMRd tumor samples." (PMID 38383773, 2024). "The frequencies of the tumor-reactive CD8+_CXCL13 and CD8+_KI67 populations were significantly positively correlated with the frequency of the IFN-producing CD4+_MKI67 population, supporting the concept of a tumor antigen-driven “help” scenario in the TME." (PMID 38383773, 2024). "FOXP1 was also reported to act as a tumor suppressor via the negative regulation of the expression of IL-7 in tumor-specific CD4 + T helper cells 7 (Th9)." (PMID 38279090, 2024). "In summary, these results suggest that the anti-tumor effects of zebularine depend on the co-existence of CD4+ and CD8+ T lymphocytes and the presence of CD4+ T cells is necessary for CTLs to kill tumor cells." (PMID 38755254, 2024). "The infiltration level analysis of KGs revealed that, KGs are significantly associate with different tumor infiltrates immune cells such as, CD8 T cell, CD4 T cell, B cell, neutrophil, macrophage and dendritic cell (DC) of GBM." (PMID 39528802, 2024). "Treatment with STYMIE #22 and #30 resulted in the highest increase in tumor‐infiltrating CD4+ T cells, CD8+ T cells, and NK cells, whereas neutrophils, macrophages, and B cells remained largely unaffected across all treatment and control groups." (PMID 38937984, 2024). "Further analysis into the spatial distribution of CD4+ and CD8+ T cells showed that the relative distribution of CD4+ T cells was increased in central compared with peripheral and non-tumor tissues in patients receiving Neo-CT compared with upfront surgery." (PMID 38335302, 2024). "We observed an increase in CD4+ tumor-infiltrating T-cells (TILs) in the MDA-MB-231 xenografts treated with MB/OVs complexes with or without pembrolizumab adjuvant treatment compared to mice injected with unprotected OVs (IT or IV) or IV with control MBs." (PMID 39769460, 2024). "Multiple doses of anti-metabolite chemotherapy increased inhibitory receptor expression on tumor infiltrating CD4+ T cells." (PMID 39343508, 2024).
tumor (continued). "This group of lymphocytes can also stimulate chronic inflammation, and thus tumor growth, and can inhibit the response of CD4+ T cells and NK cells." (PMID 39769334, 2024). "A positive correlation was observed between the expression of HKDC1 and three different types of tumor-initiating cells (TICs), namely resting memory CD4 T cells, M0 macrophages, and M1 macrophages." (PMID 38434978, 2024). "Stimulation within the tumor environment can prompt the transformation of naïve CD4+ T cells into ‘inducible’ Tregs." (PMID 39227959, 2024). "We found that anti‐CD4 treatment significantly reduced the tumor‐killing function of the T cells, and tumor regression was slower in mice treated with anti‐CD4 than in mice treated with IgG." (PMID 39225354, 2024). "The median proportion of ICOS+ CD4+ T cells in central tissues was 4-fold higher than that in non-tumor tissues and peripheral blood T cells." (PMID 38335302, 2024). "Specifically, we observed an increased CD8+ to Treg cell ratio, heightened effector functions of CD8+ TILs, and the presence of SFB-3340-specific CD4+ T cells with pro-inflammatory properties in the tumor microenvironment." (PMID 39185202, 2024). "In this study, we provided a proof of concept that redirecting the antigen specificity of tumor cells to tumor-infiltrating CD8+ and CD4+ TBYS cells effectively controls tumor progression." (PMID 38609488, 2024). "In the realm of KC, the CD4+CD25+Foxp3- T cell subset exerts its influence predominantly through its regulatory prowess within the intricate tumor immune microenvironment." (PMID 39267764, 2024). "In summary, this study provides evidence that increased tumor infiltration by CD4 + and CD8 + T cells and reduced spatial heterogeneity of these T cell populations are key markers for a response to ICB." (PMID 38918836, 2024). "CD4+ memory T cells are an antigen-experienced population that can have a role in neoantigen expression in tumor cells." (PMID 39408764, 2024). "This supports the essential role of CD4 T-cells in promoting sustained anti-tumor immune responses as well as the immunosuppressive role of Tregs and neutrophils." (PMID 39238637, 2024). "Recent findings also postulate that activated CD4+ T cells can induce inflammatory cell death, thereby managing immune‐evasive tumours." (PMID 38451000, 2024). "As MDV commonly transforms CD4+ T cells, this increase likely represents expanding tumor cells consistent with the increased tumor incidence in these chickens." (PMID 38953352, 2024). "The percentage of CD3+CD4+ T cells in the tumor microenvironment was significantly increased after treatment with A. vulgaris extract." (PMID 38920557, 2024). "Tumor-derived exosomes stimulate the development of CD4+ T cells into CD39+ regulatory T cells, which in turn leads to immunosuppression inside the tumor microenvironment (TME)." (PMID 39062506, 2024). "With the TNM staging, CD4+Tregs or CD8+Tregs were surrounded with more tumor cells in IM and TC and CD4+T cells in IM." (PMID 39093404, 2024). "Tumours with positive PD-L1 IC expression were more likely to have high Foxp3+CD4+ T cell infiltration in tumour islets." (PMID 39409156, 2024). "The development of HPV‐associated malignant tumors is linked to CD4+ T cell depletion, impacting the ability of CD8+ T cells to mount an effective immune response to HPV‐E7, crucial for tumor development and maintenance." (PMID 39240588, 2024). "Secondly, Tregs secrete anti-inflammatory cytokines like IL-10 and TGF-β, which dampen the activation and effector functions of tumor-specific CD4+ helper and CD8+ killer T cells [1154]." (PMID 39273409, 2024). "Administration of TNF⍺ to human GBM patients increased tumor necrosis and tumor-infiltrating CD4+ and CD8+ T cells." (PMID 38254796, 2024). "This led to the identification of 15 unique cell clusters comprising of CD8 and CD4 T cells, neutrophils, tumor/epithelial cells, blood vessels, DC/APCs, macrophages, and other immune clusters." (PMID 39606482, 2024).
tumor (continued). "To better understand the underlying differences between TN and HR + HER2− immune-high and -low clusters, we used gene signatures for CD8+ and CD4+ Treg (Fig. 3Aii) T cells as proxy for immune cell type abundance in the tumor." (PMID 39149486, 2024). "We focused our analysis on CD8+ and DUSP4 CD4+ T cells since these proved to contain most tumor-reactive cells and had the highest dysfunction scores." (PMID 38181797, 2024). "An immune infiltrate analysis showed that CD8 and CD4 T cells were localized in a tumor and exhibited an activated phenotype, with the presence of activated CD8 T cells correlating with positive outcomes." (PMID 38542199, 2024). "They observed significantly elevated intratumoral infiltration of CD4+ T cells and tumor-antigen–specific clonal expansion of this population." (PMID 39133651, 2024). "In contrast, the infiltrate estimation value was negatively correlated with the anti-tumor immune cells, including CD4+ T cells (p = 1.28 × 10−4), CD8+ T cells (p = 1.85 × 10−3), and B cells (p = 1.33 × 10−3)." (PMID 38392302, 2024). "In particular, EAC seems to be characterized by a greater number of tumor-infiltrating CD4+ T cells, while ESCC shows a marked enrichment of myeloid cells." (PMID 39123475, 2024). "For example, Th1 CD4+ cells show anti-tumor effects while antigen-restricted Th2 CD4+ T cells promote tumor progression." (PMID 39044834, 2024). "What is more, the percentage of CD8 + T cells as well as CD4+ T helper cells within 10 μm radius of a tumor cell (CD44v6+ ) was higher in CNA-quiet compared to CNA-other OCSCC, especially in the invasive margin." (PMID 39428388, 2024). "The serum zinc level significantly positively correlated with the percentage of CD19+CD69+ in tumor samples and CD4+CD25+ in node samples." (PMID 38256645, 2024). "The elevated levels of CD3 and CD4 indicated a close correlation between therapeutic efficacy and the levels of CD3+T and CD4+T lymphocyte infiltration in the tumor after treatment." (PMID 38751816, 2024). "Bothantigen-signaled CD8+ and CD4+ T cell clonal populations were substantiallyexpanded in the tumor." (PMID 38787961, 2024). "HVEM+ K562 cells and HVEM− Hek293 were treated first with 20 ng/100 μL of HVEM blocker using 1 × 105 cells for 2 h before being washed and then co-cultured with CFSE-labeled CD4+ T cells at a ratio of one tumor or healthy control cell to ten CFSE CD4+ T cells." (PMID 38785930, 2024). "In the context of the CRC TME, TILs represent a heterogeneous mixture of adaptive immune cells, comprising mainly anti-tumour T cells (CD4+ and CD8+ subsets) and suppressive CD4+ T cells (Treg)." (PMID 39575712, 2024). "For this purpose, we first conducted a differential expression analysis between the Treg population and all other CD4+ T cells within an intra-tumor subset of the pan-cancer scRNA-seq T cell atlas, defining a “Treg vs all” signature." (PMID 39729479, 2024). "In our previous studies, CTT was shown to induce CD4+ Th1-dominant anti-tumor immunity to sustain the long-term survival of mice." (PMID 38791188, 2024). "Bulk RNA-sequencing was performed on tumor samples from 33 dogs with either CD4+ (26/33), CD8+ (4/33), or CD4-CD8- (3/33) PTCL as diagnosed by flow cytometry, and sorted CD4+ and CD8+ lymphocytes from healthy control dogs." (PMID 38166662, 2024). "In particular, those patients with high FOXP3 expression levels in the tumor compartment and low CD4 levels in the tumor or in the stroma had higher levels of LGALS3 in tumor." (PMID 37567864, 2024). "As an indispensable member of anti-tumor immunity, CD4+ T cells promote anti-tumor immunity by assisting CD8 effector T cells or directly eliminate tumor cells by acting as cytotoxic T cells." (PMID 39104385, 2024). "In a mouse model with 4T1 tumor, the application of light and 40 led to higher suppression of tumor growth, metastatic activity, higher OS and higher CD4+ and CD8 + T cells/ Treg ratio." (PMID 39138299, 2024).
tumor (continued). "Immunohistochemistry showed decreased exhaustion markers in CD8(+) and CD4(+) T cells within the tumor, indicating enhanced T cell activity." (PMID 39459546, 2024). "Despite the presence of tumour‐reactive T cells, CD8 and CD4 T cells in cancer patients often remain inactive, leading to tumour evasion." (PMID 38520220, 2024). "We have previously shown that these naive tumour-specific CD4+ T cells can successfully eradicate established tumours in this model when activated by host APCs." (PMID 38125720, 2024). "Strikingly, immune profiling of both tumor types revealed significantly more CD4(+) and CD8(+) T cells in Cdk12KO-sgp53 versus TRAMP-C2 samples." (PMID 39368479, 2024). "This reduction is mediated by a liver-specific regulatory process, which causes significant changes in effector CD4+ and CD8+ T cells at distant tumor sites." (PMID 38774326, 2024). "In mouse model of breast tumors 4T1, PLP effectively controlled tumor growth and enhanced immune response by recruiting DC, CD8+T and CD4+T cells to the tumor microenvironment." (PMID 39364399, 2024). "Flow cytometry revealed that PDEH activates the local immune response by enhancing the ability of mature DCs to present tumor‐associated antigens to CD8+ and CD4+ T cells." (PMID 39118566, 2024). "Comparing T cell gene expression between treatments revealed a significant increase in Klrk1, Klrc2, Klrd1, Fasl, and Sema4a in CD4 T cells at the tumor site after HVJ-E/OX40 antibody injection." (PMID 39534532, 2024). "We also analyzed the clinical predictive value of the tumor-infiltrating CD4+ T-cell populations for the response to cancer therapies." (PMID 38383773, 2024). "Experimental inhibition of autophagy in myeloid-derived suppressor cells (MDSCs) in melanomas led to the efficient activation of tumor-specific CD4 T cells, impaired immunosuppressive function of MDSCs, and a significant reduction in tumor volume." (PMID 39062119, 2024). "Following H101 treatment, the patient experienced notable reduction in cardia lesions, improvement in eating obstruction, and modest activation of the local tumor immune microenvironment, fostering infiltration of CD4+ T cells." (PMID 39588306, 2024). "These tumor antigen-loaded DCs possess high antigen-presenting efficiency with sufficient exogenous costimulatory signals and can prime CD4+ T cells via peptide-MHC II complexes and CD8+ T cells via peptide-MHC I molecules." (PMID 39406966, 2024). "These polyclonal CD8+ and CD4+ antitumor T-cell responses raised against tumor neoantigens and/or TAAs would be beneficial in reducing tumor escape variants through the loss of single or multiple antigens in the tumor cell." (PMID 38962577, 2024). "Immunohistochemical staining of tumor tissue demonstrated that DI/Pep1 enhanced the expression of CD4 and improved immune function." (PMID 39545088, 2024). "CD4+ T-cell subpopulations can also enhance or suppress the anti-tumor effect of immune cells by coordinating multiple immune responses." (PMID 38649887, 2024). "CD4+ T cell responses regulate the immune cycle in tumours, and both are important in patient outcomes." (PMID 39639610, 2024). "The ability of CD4+ T cells to recognize neoantigens from mutations in oncogenes like HER2 and KRAS further supports their role in targeting tumor-specific antigens." (PMID 39457373, 2024). "This provides an opportunity for vaccine-induced neoantigen-specific CD4+ T cells to provide optimal help and stimulate tumor-specific CD8+ T cells, which can then re-enter the circulation and home to the tumors to kill malignant cells." (PMID 39040850, 2024). "Previous studies have highlighted the importance of B cells, macrophages, CD4+ T cells, and dendritic cells as crucial immune cells with a wide range of anti-tumor effects 23-25." (PMID 38370368, 2024).
tumor (continued). "DCs can phagocytose dead tumor cells and migrate to the nearby lymph nodes, where they present tumor antigens on their surface and activate CD4+ and CD8+ T cells with highly immunogenic antigens." (PMID 39085965, 2024). "The results showed a significant increase in the number of activated CD4 memory T cells, resting NK cells, and resting macrophages in the high-risk group, confirming the role of the 10 DRG-lncRNAs model in regulating tumor immune cell infiltration." (PMID 38862217, 2024). "DC matured in presence of dying tumor cells and cell surface expressed or secreted DAMPs can stimulate type 1 cytokine production and proliferation by CD4+ and CD8+ T cells." (PMID 39007281, 2024). "Like PD-1 and CTLA-4, continuous tumor-associated antigens exposure can result in high and sustained expression of LAG-3 on CD4+ and CD8+ T cells, which negatively regulate T cell expansion and lead to immune disorders, mainly manifested as T-cell exhaustion." (PMID 39252941, 2024). "ccRCC tumors have a high frequency of CD8+ and CD4+ T cells in the tumor microenvironment (TME), making them a favorable candidate for immune checkpoint blockade therapy (ICB)." (PMID 38618956, 2024). "They found a higher density of CD8+ cytotoxic T cells, FoxP3− CD4+ helper T cells, and FoxP3+ CD4+ Tregs at the tumor margin." (PMID 39683528, 2024). "In terms of the efficacy of topical SQV in cancer prevention, there appeared to be a delay in the tumor development/onset in the CD4-depleted mice." (PMID 39339897, 2024). "In patients with CRC liver metastases, we observe an inflammatory TIME enriched in CD8 and CD4 T cells and M1 macrophages, along with pro-tumor immune infiltrate of M2 macrophages, MDSCs and Tregs." (PMID 39108491, 2024). "Given the pivotal role of CD4+ T cells in tumor immune responses, our focus was directed toward investigating the significance of disulfidptosis-mediated CD4+ T cells." (PMID 38292868, 2024). "The results highlight the link between these genes and tumor immune cell infiltration, particularly with T cell CD4+ effector memory, B cells, neutrophils, macrophages, and MDSCs." (PMID 39668817, 2024). "Remarkably, the combined transfer of memory CD8+ and CD4+ T cells synergized to better control tumor growth in the NDV-GP-treated group than in monotransfer of memory CD8+ or CD4+ T cells." (PMID 38609488, 2024). "CD4+ Th cells are of growing interest in immunotherapy, but their high plasticity and ability to switch phenotypes can complicate their role in tumor immunity." (PMID 39769334, 2024). "To provide further support to the role of T cells in protecting the mice from MOC2 tumor growth in vivo, we induced depletion of either CD4+ or CD8+ T cells by treating naïve mice with specific monoclonal antibodies, as described in Materials and Methods." (PMID 39035008, 2024). "PDI-1 decreased the abundance of infiltrating FoxP3+ CD4+ T cells and consequently reduced the growth of the tumor." (PMID 38674427, 2024). "Conducting differential analysis of metabolic pathway activity within T cells and NK cells, grouped by normal and tumor tissues as criteria, revealed CD4+ T cells and CD8+ T cells as the cell subsets undergoing the most pronounced metabolic reprogramming." (PMID 38414015, 2024). "It was found that the introduction of Parabacteroides distasonis enhanced the efficacy of PD - 1 immunotherapy, as evidenced by delayed tumor growth and increased densities of CD4+ T and CD8+ T cells in the tumor." (PMID 39703512, 2024). "Although anti-PD-1 therapy increased CD4+ T cell tumor infiltration, the sublineage composition was similar to control." (PMID 38518770, 2024). "rAd5-16/E6E7Wt with or without the anti-PD-1 checkpoint inhibitor induced a significant increase in the number of CD4+ and CD8+ T cells in the tumor mass along with an increase in Treg cells (defined as CD45 + CD3 + CD4 + FoxP3+)." (PMID 39339987, 2024).